CCDC83 (coiled-coil domain containing 83)
Synonyms: HSD9; MGC34732; FLJ42119; CT148; KP-CoT-23
Tractability: No criterion of Open Targets' tractability assessment is met for any kind of drug.
Gene: Protein-coding gene on chromosome 11 (85,855,101 to 85,920,021, forward strand). Ensembl gene ENSG00000150676.
Subcellular location (Human Protein Atlas): Nucleoplasm; Vesicles
Gene Ontology:
Molecular function: protein binding
Genetic constraint (gnomAD): Loss-of-function variants: 23 observed, 25.8 expected, observed/expected ratio (o/e) 0.89, 90% interval 0.64 to 1.26. The upper end of that interval is the gene's LOEUF score, 1.26, which puts it in group 5 of 6, group 1 being the genes least tolerant of losing a copy. Missense variants: 302 observed, 281.38 expected, observed/expected ratio (o/e) 1.07, 90% interval 0.98 to 1.18. Synonymous variants: 96 observed, 90.11 expected, observed/expected ratio (o/e) 1.07, 90% interval 0.9 to 1.26.
Homologues: Orthologues: chimpanzee CCDC83 (99% identical), macaque CCDC83 (96% identical), dog CCDC83 (79% identical), pig CCDC83 (78% identical), rabbit CCDC83 (78% identical), rat Ccdc83 (66% identical), mouse Ccdc83 (63% identical), guinea pig CCDC83 (59% identical), tropical clawed frog ccdc83 (35% identical), zebrafish ccdc83 (21% identical).
Diseases named in the same sentence as CCDC83 in open-access papers:
CCDC83 is named in the same sentence as 5 diseases in open-access papers, as found by Europe PMC text mining. Sharing a sentence is not in itself a finding about the gene and the disease. The quoted sentences say what the papers report.
colon cancer (1 paper, 2021). "CCDC83 was previously reported as a CT antigen, KP-CoT-23, from colon cancer by SEREX." (PMID 34065612, 2021).
cancer (1 paper, 2023). A tumor composed of atypical neoplastic, often pleomorphic cells that invade other tissues. "A number of fusions detected by TAGET involve known cancer genes such as HNRNPA3-NFE2L2, SNRNP25-TSC2, CCDC83-PICALM, and CBLB-IDI1." (PMID 37741817, 2023).
CCDC83 also shares sentences with these, for which no sentence is quoted: brain diseases (1 paper); cognitive decline (1); infection (1).